RNASE2CP (ribonuclease A family member 2C, pseudogene)
Synonyms: ECRP
Gene: Long non-coding RNA gene on chromosome 14 (20,909,831 to 20,920,307, forward strand). Ensembl gene ENSG00000136315.
Diseases named in the same sentence as RNASE2CP in open-access papers:
RNASE2CP is named in the same sentence as 2 diseases in open-access papers, as found by Europe PMC text mining. Sharing a sentence is not in itself a finding about the gene and the disease. The quoted sentences say what the papers report.
immune diseases (1 paper, 2022). "So far, we have not found any studies on ECRP (ribonuclease A family member 2C, pseudogene) and LHFPL2 (LHFPL tetraspan subfamily member 2) in inflammatory or immune diseases." (PMID 35045818, 2022).
RNASE2CP also shares sentences with these, for which no sentence is quoted: Cryptococcal meningitis (1 paper).